FOXF1 (forkhead box F1)
Diseases named in the same sentence as FOXF1 in open-access papers (continued):
Sharing a sentence is not in itself a finding about the gene and the disease.
lung disease (8 papers, 2013 to 2024). "Hence, while effects of the loss of function of FOXF1 in lung disease and cancer are well documented, effects of the overexpression of FOXF1, specifically in the context of lung development, are not currently known." (PMID 27638768, 2016). "Therefore, small molecule compounds capable of promoting Foxf1 transcription or protecting FOXF1 protein from degradation could provide a useful therapeutic for a variety of pulmonary diseases associated with delayed lung regeneration and repair." (PMID 28878348, 2017). "The regular association of FOXF1 abnormalities with ACD/MPV suggests that detailed studies targeting the relationship between FOXF1 and SERT may provide valuable data regarding the pathomechanism of this uniformly fatal neonatal lung disorder." (PMID 28316463, 2017). "In addition, deletion in FOXF1 gene and removing part of this lincRNA lead to FOXF1 expression decrease in lung disease, which suggests that it may be a distant regulator." (PMID 29988223, 2017).
gastric cancer (7 papers, 2018 to 2023). A primary or metastatic malignant neoplasm involving the stomach. "The polymorphism of transcription factor FOXF1 is associated with the prognosis of patients with gastric cancer." (PMID 34900998, 2021). "FENDRR is transcribed from the FOXF1 promoter and considered to be one of the favorable lncRNA biomarkers for various cancers, such as liver cancer, lung squamous cell carcinoma, bladder cancer, gastric cancer and lung adenocarcinoma." (PMID 31978896, 2020). "Lnc FENDRR: FOXF1 adjacent non-coding developmental regulatory RNA (FENDRR) was found to be related to several forms of cancer such as breast, prostate and gastric cancer and is related to FOXF1 expression, a key factor of embryonic vasculature formation." (PMID 37762249, 2023). "Our data showed that the expression of FOXM1 was significantly reduced in PAX8-overexpressing gastric cancer cells, but FOXC2, FOXF1, and FOXL1 remained unchanged." (PMID 30021604, 2018).
Esophageal atresia (6 papers, 2009 to 2024). A developmental defect resulting in complete obliteration of the lumen of the esophagus such that the esophagus ends in a blind pouch rather than connecting to the stomach. "Patients having undergone a repair of their esophageal atresia in the neonatal period were found to have an increased risk of EoE, with microdeletion involving the Forkhead box transcription factor (FOXF1), as a common genetic abnormality." (PMID 39274254, 2024). "The lack of intestinal atresia in group 3 suggests that either FOXC2 or FOXL1 may also contribute to this phenotype in humans, despite the fact that, in mice, haploinsufficiency for Foxf1 alone is associated with esophageal atresia." (PMID 19500772, 2009). "This contrasts with heterozygous Foxf1 null mice, which have esophageal atresia and tracheo-esophageal fistula on selected genetic background (CD1), but in which neither intestinal malrotation, nor indeed any other GI tract anomaly, have been reported." (PMID 19822228, 2010).
lung adenocarcinoma (6 papers, 2016 to 2026). A carcinoma that arises from the lung and is characterized by the presence of malignant glandular epithelial cells. "In human pulmonary arterial endothelial cells (HPAEC), the efficient shRNA-mediated inhibition of FOXF1 decreased LEF1 mRNA but increased growth of spheroids formed by human H-441 lung adenocarcinoma cells and FOXF1-deficient HPAECs." (PMID 38589650, 2024). "In conclusion, our data support that FENDRR and FOXF1 expression is decreased in lung adenocarcinoma and should be considered as new potential diagnostic/prognosis biomarkers." (PMID 32284793, 2020). "Interestingly, we found that FENDRR and FOXF1 had also a prognosis value since their high expression values were associated with a better clinical outcome in lung adenocarcinomas." (PMID 32284793, 2020). "In contrast, only 5–10% of endothelial cells expressed FOXF1 in human lung adenocarcinomas and squamous cell carcinomas (SCC)." (PMID 38589650, 2024). "lncRNA FENDRR and FOXF1 are also prognostic factors for the survival in patients with lung adenocarcinoma." (PMID 33869042, 2021). "Consistently, the significantly low expression of FOXF1 in lung adeno-carcinomas (LUAD) and lung squamous carcinomas (LUSC) was also observed in The Cancer Genome Atlas (TCGA)." (PMID 27577075, 2016). "Next, we searched for the presence of promoter hypermethylation by MSP analysis at FOXF1 in 10 lung adenocarcinoma samples and their adjacent normal tissues, aberrant promoter hypermethylation was detected in 2 of 10 lung adenocarcinoma patients (2/10, 20%)." (PMID 32284793, 2020). "Nuclear β-CATENIN and downstream targets of WNT/β-catenin pathway was decreased in TECs within human lung adenocarcinomas and squamous cell carcinomas (SCC), coinciding with reduced FOXF1 expression in TECs." (PMID 38589650, 2024). "We found FENDRR and FOXF1 expression was downregulated in lung adenocarcinomas compared to adjacent normal lung tissues and that FENDRR mRNA expression levels correlated positively with FOXF1 expression." (PMID 32284793, 2020). "In the present study, we have investigated FENDRR and FOXF1 expression by qRT-PCR and RNA-FISH assays in lung adenocarcinoma patients." (PMID 32284793, 2020). "Further studies revealed that upregulation of FOXF1/MFAP4 promoted anti-tumor immune responses through augmented dendritic cell and CD4+ T cell infiltration, facilitating crosstalk between lung adenocarcinoma and immune cells, and induction of multiple anti-tumor immune pathways." (PMID 41596347, 2026).
prostate carcinoma (6 papers, 2014 to 2022). A carcinoma that arises from epithelial cells of the prostate gland. "FOXF1 was first implicated as a tumor suppressor when it was shown to be expressed at low levels in prostate cancer." (PMID 25237908, 2014). "Genomic deletions in FOXF1 gene locus have been found in prostate cancer samples, whereas epigenetic inactivation of FOXF1 promoter has been reported for breast invasive ductal carcinomas." (PMID 26625197, 2016). "The functions of FOXF1 remain to be determined, yet recent studies have implicated its role in lung regeneration by targeting genes of ECM and cell cycle progression, as well as promoting prostate cancer growth via the MAPK pathway." (PMID 30119690, 2018). "FOXF1 has a positive correlation with lymph node metastasis of NSCLC and promotes the progression of prostate cancer." (PMID 30360388, 2018).
hydronephrosis (5 papers, 2013 to 2025). Collection of urine in the renal pelvis that results in dilatation of the renal pelvis and calyces. "Patients with ACD/MPV and hydronephrosis had already been described with mutations in the FOXF1 gene by Stankiewicz and colleagues, as well as with 16q24.1 microdeletion in a case reported by Zufferey and colleagues." (PMID 24829819, 2013). "Two fetuses with hydronephrosis associated with ACDMPV, caused by CNV deletions involving FOXF1 and its enhancer, have also been described." (PMID 36980834, 2023). "In summary, we present the first Polish patient with ACDMPV and hydronephrosis, in which prenatal genetic testing revealed a de novo CNV deletion at 16q24.1, involving FOXF1." (PMID 36980834, 2023).
keloid (5 papers, 2021 to 2024). An irregularly shaped, elevated mark on the skin caused by deposits of excessive amounts of collagen during wound healing. "FOXF1 is highly expressed in both endothelial cells and fibroblasts, suggesting that FOXF1 is involved in chronic inflammation following tissue injury and inhibits collagen deposition and fiber proliferation in keloid formation." (PMID 38444850, 2024). "MiR-152-3p has been reported to regulate cellular proliferation, invasion, and extracellular matrix expression by targeting forkhead box protein F1 (FOXF1) in keloid fibroblasts." (PMID 38139016, 2023). "For instance, miR-152-3p can promote cell proliferation and invasion in the keloid fibroblasts by targeting Foxf1." (PMID 35456382, 2022). "In previous studies, miR-152-3p was discovered to modulate cell proliferation and invasion by targeting forkhead box F1 (FOXF1) in keloid fibroblasts." (PMID 34374627, 2021). "The downregulation of FOXF1 and LPAR1 in keloid patients could be caused by the inactivation of E2F1 and SP1 due to mutations or other factors, or by the effect of the three miRNAs." (PMID 38444850, 2024).
pulmonary hypertension (5 papers, 2014 to 2024). Increased pressure within the pulmonary circulation due to lung or heart disorder. "The identification of reduced FOXF1 may partially explain angiogenesis deficiency in pulmonary hypertension." (PMID 36277750, 2022). "Interestingly, endothelin induced collagen remodeling has been reported in a mouse model of pulmonary hypertension, indicating that the increased endothelin-1 signaling in Foxf1+/− lungs may be causing an increase in collagen production." (PMID 24722050, 2014). "FOXF1 with ACTA2 was associated with Intestinal Malrotation (HP:0002566, q = 1.351x10-2) and Pulmonary Hypertension (HP:0002092, q = 2.318x10-2)." (PMID 39480826, 2024). "Lung EC targeted delivery of Foxf1 to reoxygenated EC-Bmpr2-/- mice repairs DNA damage, induces angiogenesis and reverses pulmonary hypertension." (PMID 37989727, 2023). "This was reinforced by our studies in the EC-Bmpr2-/- mice where targeted expression of Foxf1 using an AAV vector engineered to be delivered to lung EC prevented persistent pulmonary hypertension during reoxygenation after hypoxia." (PMID 37989727, 2023). "In EC-Bmpr2-/- mice, directing Foxf1 to lung EC during reoxygenation restored normal peripheral pulmonary arteries and allowed for the regression of pulmonary hypertension." (PMID 37989727, 2023). "Non-invasive methods such as DNA sequencing and FOXF1 analysis are helpful in the clinical diagnosis of ACD/MPV especially in early infants with respiratory distress and pulmonary hypertension." (PMID 33832123, 2021). "Delivery of Foxf1 to the pulmonary vascular EC23 during reoxygenation of EC-Bmpr2-/- mice resulted in the repair of DNA damage, in the restoration of angiogenesis genes required for the regeneration of normal pulmonary arteries, and in the reversal of pulmonary hypertension." (PMID 37989727, 2023).
cystic hygroma (4 papers, 2012 to 2025). A benign lymphatic neoplasm usually arising from the neck and characterized by cystic dilation of the lymphatic vessels. "The first prenatal deletion involving FOXF1 at 16q24.1 was identified in a fetus with cystic hygroma, a single umbilical artery, and fetal hydrops." (PMID 36980834, 2023). "We report the prenatal diagnosis of cystic hygroma that was subsequently identified to have haploinsufficiency of the FOXF1 and FOXC2 genes via array comparative genomic hybridization (aCGH)." (PMID 23074687, 2012). "There has been one prenatal case reported in the literature with septated cystic hygroma, fetal hydrops, and a single umbilical artery presented at the 18th weeks of gestation, in which aCGH identified a deletion of 1,1 Mb in size, including both FOXF1 and FOXC2." (PMID 27846804, 2016).
osteosarcoma (4 papers, 2019 to 2023). A usually aggressive malignant bone-forming mesenchymal neoplasm, predominantly affecting adolescents and young adults. "To identify the potential downstream target genes related to lincFOXF1 in osteosarcoma, we conducted qRT‐PCR to assess expression of multiple molecules (such as N‐cadherin, Integrin, CD44, ICAM‐1, Vimentin, Fibronectin, GIT1 and FOXF1) in osteosarcoma cells after gain or loss of lincFOXF1 function." (PMID 32945076, 2020). "For instance, circNASP inhibits the availability of miR-1253 and thus promotes the expression of FOXF1 in osteosarcoma cells, stimulating their proliferative and invasive activities." (PMID 36632453, 2023). "Overexpression of circNASP in osteosarcoma could relieve its inhibition of FOXF1 by sponging miR-1253 and then promoting cell proliferation, cell cycle progression, and invasion through the circNASP/miR-1253/FOXF1 axis." (PMID 30996117, 2019).
esophageal adenocarcinoma (3 papers, 2015 to 2017). A malignant tumor with glandular differentiation arising predominantly from Barrett mucosa in the lower third of the esophagus. "In a previous study, the SNP rs2178146 in FOXF1, a member of the forkhead family of transcription factors, was associated with susceptibility to esophageal adenocarcinoma." (PMID 28404937, 2017). "In addition to these markers, we genotyped three further FOXF1 SNPs that have been previously implicated in the GWAS on Barrett’s esophagus 6 resulting in a total of 90 SNPs in the replication study." (PMID 26383589, 2015). "In addition, rs9936833, which was genome-wide significantly associated with the Barrett’s esophagus GWAS 6 and is located near FOXF1 on chromosome 16q24, was EAC associated (P1-d.f. = 0.045)." (PMID 26383589, 2015). "Furthermore, the BEACON study refined a previously reported association with Barrett’s esophagus 6 near the transcription factor forkhead box F1 (FOXF1) gene on chromosome 16q24." (PMID 26383589, 2015). "Additionally, some reports have shown that rs12100561 (C14orf143), rs2178146 (FOXF1), and rs1050631 (SLC39A6) are associated with increased susceptibility to hepatocellular carcinoma, esophageal adenocarcinoma, and esophageal squamous-cell carcinoma, respectively." (PMID 28404937, 2017). "In addition, three SNPs near FOXF1 (in total eight SNPs) that have been highlighted in the BEACON study and in another GWAS on Barrett’s esophagus 6 were genotyped." (PMID 26383589, 2015).
hepatocellular carcinoma (3 papers, 2019 to 2021). A malignant tumor that arises from hepatocytes. "Loss of FOXF1 has been linked to increased invasiness of hepatocellular cancer cells." (PMID 33277571, 2020). "In the advanced disease state of hepatocellular carcinoma (HCC), which is associated with significant fibrotic depositions, FOXF1 expression has been shown to be significantly decreased." (PMID 30670377, 2019).
hypoplastic left heart syndrome (3 papers, 2009 to 2023). Hypoplastic left heart syndrome (HLHS) refers to the abnormal development of the left-sided cardiac structures, resulting in obstruction to blood flow from the left ventricular outflow tract. "In contrast to the association of point mutations in FOXF1 with bowel malrotation, microdeletions of FOXF1 were associated with hypoplastic left heart syndrome and gastrointestinal atresias, probably due to haploinsufficiency for the neighboring FOXC2 and FOXL1 genes." (PMID 19500772, 2009). "NKX2-5, which has been associated with hypoplastic left heart syndrome, was upregulated in ACDMPV patients with deletion of FOXF1 and its enhancer." (PMID 34315444, 2021). "In contrast to SNVs within FOXF1 and CNV deletions involving only the FOXF1 enhancer, larger-sized deletions involving FOXF1 and the adjacent, oppositely oriented lncRNA gene FENDRR have additionally been associated with hypoplastic left heart syndrome and single umbilical artery (SUA)." (PMID 37888207, 2023).
leukemia (3 papers, 2018 to 2023). A malignant (clonal) hematologic disorder, involving hematopoietic stem cells and characterized by the presence of primitive or atypical myeloid or lymphoid cells in the bone marrow and the blood. "For example, GATA1 partners with HNF1 in hematopoietic progenitor cells; with PPARA:RXRA in leukemia; with SRF, CDX and FOXP3 in primary T-cells; with SRY, NKX2-1, FOXF1, OCT4 and ZBTB16 in differentiated ESCs and with TAL1:TCF3 motif co-occurring in various fibroblasts." (PMID 30142147, 2018).
liver fibrosis (3 papers, 2019 to 2024). "Our studies suggest that maintaining Foxf1 expression can be beneficial in patients with advanced liver fibrosis to inhibit fibrotic responses and decrease the risk of liver tumorigenesis." (PMID 30670377, 2019). "Altogether, FOXF1 prevents aberrant ECM depositions during hepatic fibrosis by repressing pro-fibrotic gene transcription in myofibroblasts and HSCs." (PMID 30670377, 2019). "During chronic liver injury, deletion of Foxf1 in MFs exacerbated hepatic fibrosis, increased collagen deposition and stimulated expression of profibrotic genes in the liver tissue." (PMID 30670377, 2019). "Our studies indicate that Foxf1 expression in MFs is critical to prevent MF accumulation and collagen deposition during liver fibrosis." (PMID 30670377, 2019). "Using this model, we demonstrated that Foxf1 expression in MFs is necessary to inhibit hepatic fibrosis and maintain the balance of collagen depositions, through transcriptional repression of pro-fibrotic genes." (PMID 30670377, 2019). "In the current study, we utilized a conditional genetic mouse model to delete Foxf1 in MFs during CCl4-induced hepatic fibrosis which shares multiple histological similarities with human disease." (PMID 30670377, 2019). "Altogether, FOXF1 expression in myofibroblasts is essential to inhibit liver fibrosis after chronic liver injury." (PMID 30670377, 2019). "In the present study, we found that the deletion of Foxf1 in MFs during chronic CCl4-mediated injury exacerbated liver fibrosis, increased collagen deposition and stimulated expression of pro-fibrotic genes." (PMID 30670377, 2019). "In the present study, we generated αSMACreER;Foxf1fl/fl mice to conditionally inactivate Foxf1 in myofibroblasts during carbon tetrachloride-mediated liver fibrosis." (PMID 30670377, 2019). "Thus, the possible cross talk and mutual regulations between Foxf1 and Fendrr in both the physiological state and pathological processes of liver fibrosis remain to be investigated in future." (PMID 38762176, 2024). "Therefore, decreased MMP9 activity can contribute to increased liver fibrosis in αSMACreER;Foxf1−/− mice." (PMID 30670377, 2019). "FOXF1 prevents aberrant extracellular matrix depositions during hepatic fibrosis." (PMID 30670377, 2019). "To investigate the role of Foxf1 in liver fibrosis, we utilized a conditional knockout approach." (PMID 30670377, 2019). "Previous studies have shown that the Forkhead box F1 (FOXF1) transcription factor is expressed in HSCs and stimulates their activation during acute liver injury; however, the role of FOXF1 in the progression of hepatic fibrosis is unknown." (PMID 30670377, 2019). "Thus, deletion of Foxf1 from MFs accelerates liver fibrosis after chronic liver injury." (PMID 30670377, 2019). "To date, there have been contradictory reports on the role of Foxf1 in HSC activation and liver fibrosis, probably due to the utilization of different animal model of liver fibrosis or the methods of manipulating Foxf1 expression in vivo." (PMID 38762176, 2024). "ECM-related proteins were identified as novel FOXF1 transcriptional targets, suggesting that FOXF1 plays an important role in the regulation of ECM and collagen deposition during the progression of hepatic fibrosis." (PMID 30670377, 2019). "Our studies suggest that FOXF1 inhibits production of collagen and ECM during the progression of liver fibrosis." (PMID 30670377, 2019).
non-small cell lung carcinoma (3 papers, 2020 to 2024). A group of at least three distinct histological types of lung cancer, including non-small cell squamous cell carcinoma, adenocarcinoma, and large cell carcinoma. "FOXF1 was highly expressed in normal lung vasculature but was decreased in TEC within non-small cell lung cancers (NSCLC)." (PMID 38589650, 2024). "Based on our results, it could be inferred that highly expressing FOXF1 inhibits non-small-cell lung cancer growth via activating tumor suppressor p21, leading to cell-cycle arrest at the G1 phase." (PMID 32370197, 2020).
bladder cancer (2 papers, 2020 to 2024). "In murine models of orthotopic xenografts, using human bladder cancer cell lines, FOXF1 was found to be under-expressed in metastatic implants compared to primary cancers." (PMID 38540132, 2024).